IL13RA1 (interleukin 13 receptor subunit alpha 1)
Description:
Binds with low affinity to interleukin-13 (IL13). Together with IL4RA can form a functional receptor for IL13. Also serves as an alternate accessory protein to the common cytokine receptor gamma chain for interleukin-4 (IL4) signaling, but cannot replace the function of IL2RG in allowing enhanced interleukin-2 (IL2) binding activity.
Synonyms: CT19; CD213a1; IL-13Ra; NR4
Tractability: Antibody: its Gene Ontology location is reachable by antibodies, with high confidence; UniProt predicts a signal peptide or a membrane-spanning region. PROTAC: ubiquitination databases record sites on it; its protein half-life has been measured. Other modalities: a drug acting on it is in phase 2 or 3 trials.
Gene: Protein-coding gene on chromosome X (118,727,133 to 118,794,535, forward strand). Ensembl gene ENSG00000131724.
Subcellular location: Membrane
Pathways (Reactome):
Immune System: Interleukin-4 and Interleukin-13 signaling
Gene Ontology:
Molecular function: interleukin-13 receptor activity; protein binding; cytokine binding; cytokine receptor activity
Biological process: cell surface receptor signaling pathway via JAK-STAT; interleukin-13-mediated signaling pathway; positive regulation of tyrosine phosphorylation of STAT protein; cell surface receptor signaling pathway; cytokine-mediated signaling pathway; interleukin-4-mediated signaling pathway; positive regulation of leukocyte differentiation
Cellular component: interleukin-13 receptor complex; interleukin-4 receptor complex; plasma membrane; external side of plasma membrane; receptor complex; membrane
Homologues: Orthologues: chimpanzee IL13RA1 (99% identical), macaque IL13RA1 (96% identical), rabbit IL13RA1 (86% identical), dog IL13RA1 (85% identical), pig IL13RA1 (84% identical), guinea pig IL13RA1 (82% identical), mouse Il13ra1 (75% identical), rat Il13ra1 (74% identical), tropical clawed frog il13ra1 (29% identical), zebrafish il11ra (13% identical), zebrafish ghra (11% identical), zebrafish ghrb (10% identical), and 1 more. Paralogues in human: IL3RA (16% identical), LIFR (15% identical), IL6ST (15% identical), PRLR (14% identical), LEPR (14% identical), CSF3R (13% identical), IL13RA2 (13% identical), CRLF2 (12% identical), GHR (12% identical), OSMR (12% identical), CSF2RA (11% identical), CRLF1 (11% identical), and 11 more.
Diseases named in the same sentence as IL13RA1 in open-access papers:
IL13RA1 is named in the same sentence as 106 diseases in open-access papers, as found by Europe PMC text mining. Sharing a sentence is not in itself a finding about the gene and the disease. The quoted sentences say what the papers report.
asthma (12 papers, 2011 to 2025). "These lung-specific effects of IL-13 are also consistent with other work showing that pulmonary eosinophilia is impaired in IL-13Rα1–deficient mice during asthma." (PMID 34127548, 2021). "MiR-155-5p, has been implicated to play varied roles in asthma in many different cell types and can directly target IL-13Rα1 mRNA preventing translation into protein." (PMID 32477356, 2020). "IL13RA1 has been implicated in eosinophilic esophagitis and asthma pathogenesis." (PMID 33804792, 2021). "Amongst these genes, we find IL13 and its receptor IL13RA1 which are known the be driving the mucus hypersecretion phenotype in asthma." (PMID 33731770, 2021). "Decreased IL13RA1 expression is surprising in the context of asthma but this could be due to a compensatory response to continued eosinophilia and IL13/IL4 exposure in the lung." (PMID 29228930, 2017). "The targets of the FEO‐03 network, IL13, and functional partners IL13RA1, IL13RA2, IL4R, IL6, and TNF were presented in a red box from the asthma diagram of KEGG Pathways." (PMID 40777200, 2025). "Also, several inflammatory mediators, of potential relevance to asthma, such as SOCS1, IL1B, IL13RA1 and CCL26 could be potentially affected, directly or indirectly by one or more microRNAs of this list." (PMID 25360780, 2014).
breast carcinoma (10 papers, 2016 to 2025). "In breast cancer, higher expression of IL13Rα1 was significantly associated with shorter OS and disease-specific survival." (PMID 33419470, 2021). "In addition, elevated expression of IL4Rα and/or IL13Rα1 were associated with poor prognosis of glioblastoma, mesothelioma, breast cancer, renal cell carcinoma, and oral cavity squamous cell carcinoma patients." (PMID 33419470, 2021). "Studies using a 4T1 breast cancer mouse model have shown that ILC2-derived IL-13 promotes 4T1 lung metastasis via the activation of the IL-13Rα1 expressed in MDSCs." (PMID 35805039, 2022). "Another study demonstrated that high expression of the plasma membrane receptor for IL-13 (IL-13Rα1) was observed in breast cancer patients with HER2 positivity." (PMID 33178603, 2020). "Previous research has indicated that PGK1, SDC1, SDC3, NUP43, and IL13RA1 may contribute to the development and progression of breast cancer." (PMID 39590319, 2024). "Taken together, our findings suggest that stage-dependent ILC2 activation might induce differential functioning of MDSCs through IL-13/IL-13Rα1 signaling during cancer progression from micro- to macrometastasis in breast cancer lung metastasis." (PMID 35805039, 2022). "Overexpressed IL13Rα1 in tumor cells is closely related to patients with breast cancer." (PMID 31540495, 2019). "However, it remains unclear whether activating ILC2s would mediate similar antitumor effects in lung metastasis of breast cancer, since MDSCs are activated via IL-13/IL-13Rα1 signaling to induce pro-tumor effects." (PMID 35805039, 2022). "IL13RA1 expression was not correlated with survival across all breast cancer subtypes; however, there was a significant difference in survival observed particularly in the basal subtype and to a lesser extent in the luminal A subtype." (PMID 38731867, 2024). "Here, we speculate that the immunosuppressive activity of MDSCs was induced by Arg1, rather than iNOS, through IL-13/IL-13Rα1 signaling in breast cancer lung metastasis." (PMID 35805039, 2022). "Interestingly, IL-13Rα2 but not IL-13Rα1 was reported to be involved in pancreatic and breast cancer metastasis." (PMID 27533463, 2016).
Allergy (6 papers, 2013 to 2025). An allergy is an immune response or reaction to substances that are usually not harmful. "The expression of allergy genes (IL-13RA1, IL-33, FCERIG, CHIL1) was also enhanced in the OVA + PM group when compared to the OVA group indicating the possible exacerbation of AD." (PMID 32846909, 2020). "Signaling initiated by IL-13Rα1 in cell types other than B cells may also be relevant for atopic and allergic diseases." (PMID 40614216, 2025).
glioma (6 papers, 2018 to 2023). A benign or malignant brain and spinal cord tumor that arises from glial cells (astrocytes, oligodendrocytes, ependymal cells). "The specificity for IL13Rα2 (which is glioma-restricted) over the more broadly expressed IL13Rα1 is driven by a point mutation (E13Y) that gives a 50-fold higher affinity for IL13Rα2 and a 5-fold lower affinity for IL13Rα1/IL4Rα over wild-type IL13." (PMID 37846297, 2023). "The affinity of IL-13 to IL-13RA2 was found to be stronger than that to IL-13RA1, which inhibits the IL-13RA1/IL-4R signaling pathway, suggesting IL-13RA2 as a powerful target for anti-glioma therapy." (PMID 36466873, 2022). "When IL-13Rα2 expression was compared between lower-grade glioma and high-grade GBM, both IL-13Rα1 and IL-13Rα2 gene expression levels were significantly lower in lower-grade glioma compared with GBM." (PMID 29168083, 2018). "Jing Han and his colleagues showed that high IL-13Rα1 with or without IL-13Rα2 expression was associated with poor prognosis in patients with high-grade gliomas." (PMID 33553434, 2021). "Furthermore, when IL-13Rα2 expression was compared between lower-grade glioma and high grade GBM, both IL-13Rα1 and IL-13Rα2 gene expression levels were significantly lower in lower-grade glioma compared with GBM." (PMID 29168083, 2018).
glioblastoma (5 papers, 2002 to 2024). The most malignant astrocytic tumor (WHO grade IV). "Higher expression of IL13Rα1 mRNA was associated with poor prognosis of glioblastoma patients." (PMID 33419470, 2021). "We observed expression of IL13Rα1 in the colorectal cancer cell line HT-29 and the glioblastoma cell lines U251 and U87 in both cellular extracts and plasma membrane." (PMID 30318506, 2018). "We have previously shown that a large number (41 of 46 samples) of glioblastoma biopsy samples or primary cell cultures are positive for IL-4Rα and IL-13Rα1 chains as determined by RT–PCR and immunofluorescence analyses." (PMID 11870521, 2002). "Interleukin IL-13 is expressed in glioblastoma; it binds to two receptors, IL-13Rα1 and IL-13Rα2, and mediates a variety of different effects on various cell types, including B cells, neutrophils, monocytes, natural killer cells, endothelial cells, and fibroblasts." (PMID 38003396, 2023). "Furthermore, there was a positive correlation between the expression of mRNA IL4Rα and IL13Rα1 in glioblastoma multiform." (PMID 33419470, 2021). "Therefore, since the D1 peptide could also block the binding of IL13 to the more widespread receptor IL13Rα1, we investigated the presence of IL13Rα1 in different colorectal cancer and glioblastoma cell lines." (PMID 30318506, 2018).
pancreatic cancer (5 papers, 2005 to 2024). "We now have demonstrated that the loss of IL-13Rα1 induces apoptosis in pancreatic cancer cells." (PMID 35409019, 2022). "Downregulation or loss of NDUFA1 expression is a known consistent feature of basal cell carcinoma, while reduced expression of IL13RA1 has been associated with apoptosis and promotion of epithelial to mesenchymal transition (EMT) in pancreatic cancer." (PMID 38694815, 2024). "The effect of IL-13Rα1-downregulation on pancreatic cancer cell proliferation was investigated by cell viability assay (MTT assay) and colony formation assay." (PMID 35409019, 2022). "Now, increasing evidence indicates salient activities of IL-4, IL-13 and their specific receptor complex IL-4Rα/IL-13Rα1 in carcinomas including pancreatic cancer." (PMID 35409019, 2022). "Overall, IL-13Rα1 plays a critical and diverse role in the survival and migration of cultured pancreatic cancer cells." (PMID 35409019, 2022). "The protein levels of IL-13Rα1, IL-4Rα and γc in cultured human pancreatic cancer cell lines A818-6, AsPC-1, Capan-1, PANC-1 and MIA PaCa-2, were determined by Western blot (WB)." (PMID 35409019, 2022). "All pancreatic cancer cell lines expressed IL-13Rα1 (47 kDa), IL-4Rα (140 kDa) and γc (64 kDa) at various levels." (PMID 35409019, 2022). "Wounds of IL-13Rα1-KD clones, unlike the control groups, were closed at 48h, which indicates that IL-13Rα1-downregulation enhances the mobility of pancreatic cancer cells." (PMID 35409019, 2022). "In line with previous results for IL-4Rα, our data showed an inhibitory effect of IL-13Rα1-downregulation on cell viability/growth in two different pancreatic cancer cell lines." (PMID 35409019, 2022). "Previous results are indicative of a contributing role of the IL-13/IL-13Rα1 axis to pancreatic cancer." (PMID 35409019, 2022). "IL-4 and IL-13 act on pancreatic cancer cells mainly through their receptor heterodimers IL-4-receptor-alpha (IL-4Rα) and IL-13Rα1, termed type II IL-4R, via signal pathways of STAT3/6, IRS-ERK/PI3K-Akt and mTOR." (PMID 35409019, 2022). "The differential expression of IL-4Rα and IL-13Rα1 has to be taken into account when considering a cytokine-targeted therapy in pancreatic cancer." (PMID 35409019, 2022). "The expression of IL-13Rα1 in pancreatic cancer cells including ASPC-1, Capan-1, MIA PaCa-2, COLO-357, PANC-1, T3M4, and BxPC-3 was determined on both protein and mRNA levels." (PMID 33804263, 2021). "Several studies have shown the excessive existence of the IL-13Rα1 and IL-13Rα2 chains in pancreatic cancer." (PMID 33804263, 2021). "The findings of this study may help to better understand the different functions and mechanisms involving IL-13Rα1 in pancreatic cancer progression." (PMID 35409019, 2022). "Thus, IL-13Rα1-downregulation reduced pancreatic cancer cell survival in both anchorage-dependent and -independent assays." (PMID 35409019, 2022). "Overall, our results indicate the vital role of IL-13Rα1 in the progression of pancreatic cancer." (PMID 35409019, 2022). "Furthermore, as shown in the soft agar assay, the number, as well as the size of the colonies formed by pancreatic cancer cells in soft agar after 21 days, was decreased in the IL-13Rα1-KD clones." (PMID 35409019, 2022). "IL13Rα2 was hypothesized to be a decoy receptor for IL13Rα1 and the type II IL-4R complex, but updated evidence suggests that IL-13 may signal through IL-13Rα2 to promote pancreatic cancer cell proliferation and invasion." (PMID 33804263, 2021). "We detected both receptor chains participating in the type-II-IL-4-receptor (140 kDa IL-4Rα and 47 kDa IL13Rα1) in 7 different pancreatic cancer cell lines, derived from both pancreatic primaries (BxPC-3, MIAPaCa-2, PANC-1) as well as from metastases (AsPC-1, Capan-1, COLO-357, T3M4)." (PMID 28350325, 2017).
pancreatic cancer (continued). "It is also possible that the expression of the IL-13Rα1 chain, which associates with the IL-4Rα chain to form a functional receptor, may influence the effects of exogenous IL-4 although MIA PaCa-2 cells as well as the other pancreatic cancer cells lines express IL-13Rα1." (PMID 15714203, 2005). "All tested pancreatic cancer cell lines AsPC-1, BxPC-3, Capan-1, COLO-357, MIAPaCa-2, PANC-1 and T3M4 expressed both IL-4Rα (140 kDa) and IL-13Rα1 (47 kDa) at various expression levels." (PMID 28350325, 2017).
allergic rhinitis (4 papers, 2013 to 2020). Inflammation of the nasal mucous membranes caused by an IgE-mediated response to external allergens. "For example, reduction of IL13Rα1 expression by miR-143 has been shown to reduce IL-13-induced mucus production in nasal epithelial cells from patients with allergic rhinitis." (PMID 29438285, 2018). "MicroRNA-143 (miR-143) was found to be downregulated in allergic rhinitis, and bioinformatics analysis predicted that IL-13Rα1 was a target gene of miR-143." (PMID 23965966, 2013).
colorectal cancer (4 papers, 2018 to 2025). A primary or metastatic malignant neoplasm that affects the colon or rectum. "Integrating miR-155, VEGF, and immune-regulatory markers (e.g., SOCS1, BCL-6, IL-13RA1) into biomarker-based colorectal cancer detection models could enhance early detection and risk assessment." (PMID 41345725, 2025). "Higher levels of IL4, IL4Ra, and IL13Ra1 mRNA expression were detected in gastric than colorectal cancer, which, taking into account their association with tumor progression and aggressiveness may contribute to worse prognosis associated with gastric cancers." (PMID 32512917, 2020). "In colorectal cancer cells, IL13 induced epithelial-to-mesenchymal transition through the STAT6 pathway and was reversed with knock-down of IL13Rα1." (PMID 33419470, 2021).
acne (3 papers, 2024 to 2025). An inflammatory process of the sebaceous glands which is characterized by comedones, nodules, papules and/or pustules on the skin. "We activated IL-13RA1 by IL-13 in the HaCaT cell line, which resulted in the dysregulation of genes associated with hyperkeratinization, further implicating its role in acne development." (PMID 38854033, 2024). "Concurrently, treating human HaCaT cells with IL-13 to activate IL-13RA1 signaling resulted in dysregulation of KRT16, KRT17, and FLG expression, which are associated with hyperproliferation-associated phenotypes in acne." (PMID 38854033, 2024). "Activation of GRN and IL-13RA1 exacerbates inflammation and hyperkeratinization both of which are critical in acne progression." (PMID 38854033, 2024). "Our subsequent focus centered on examining the roles of GRN in TREM2 macrophages and IL-13RA1 in keratinocyte basal cells given their consistent alterations across donors and potential importance in acne development." (PMID 38854033, 2024). "Our data collectively suggest that inflammation and hyperkeratinization, driven by common dysregulated GRN and IL13RA1 may be pivotal in acne development." (PMID 38854033, 2024). "Our findings suggest that GRN and IL-13RA1 are key players in the inflammation and hyperkeratinization process during acne development, highlighting their potential as novel therapeutic targets for acne treatment." (PMID 38854033, 2024). "Collectively, these data suggest that IL-13RA1 signaling may play a significant role in driving the dysregulation of genes related to hyperkeratinization, contributing to the development of acne in human skin." (PMID 38854033, 2024). "Next, to spatially localize GRN and IL-13RA1 expression in acne skin, we used our previously published Seq-Scope sequencing dataset obtained from acne lesions and segmented the histological area using 10 μm-sided square grids, each grid detected an average of 145 genes across 3558 grids." (PMID 39143467, 2024). "Subsequently, we focused on the function of GRN and IL-13RA1 in TREM2 macrophages and keratinocytes as these cells participate in inflammation and hyperkeratinization in the early stages of acne development." (PMID 38854033, 2024). "Together, our findings shed light on the complex interplay between inflammation and hyperkeratinization in acne pathogenesis, while also highlighting GRN and IL-13RA1 as promising therapeutic targets for acne." (PMID 38854033, 2024).
colon carcinoma (3 papers, 2016 to 2020). "Like IL4Ra, however, IL13Ra1 expression in colonic cancer cells was uniformly downregulated under hypoxia." (PMID 32512917, 2020). "Recent reports showed that IL4Rα and IL13Rα1 are overexpressed and activated in various types of epithelial tumor such as malignant glioma, ovarian, lung, pancreas, and colon carcinoma." (PMID 31540495, 2019). "Consistently, previous studies also reported that IL-13Rα2 mRNA did not be detected by RT-PCR in HT29/B6 colon cancer cells and IL-13/IL-13Rα1 pathway was shown to play a central role in the regulation of intestinal epithelial architecture and function." (PMID 27533463, 2016). "Moreover, the authors showed an inhibition of colonic cancer cell proliferation induced by IL-13 by silencing IL13Ra1, but not IL13Ra2 gene." (PMID 32512917, 2020).
lung carcinoma (3 papers, 2021 to 2022). "The protein expression of CHI3L1, IL‐13Rα1, and IL‐13Rα2 was significantly higher in tumor tissues than in normal tissues of lung cancer patients." (PMID 34758182, 2022). "Consistently, nuclear expression of IL4Rα and IL13Rα1 was presented in soft tissue sarcomas, clear cell renal cell carcinoma, squamous cell carcinoma, and lung cancer." (PMID 35207737, 2022). "In addition, the expression of IL4Rα and/or IL13Rα1 was observed in both the cytoplasm and nuclei of human cancer tissue samples, such as clear cell renal cell carcinoma, squamous cell carcinoma, and lung cancer." (PMID 33419470, 2021). "In the tissue samples from lung cancer patients, the protein expression of CHI3L1, IL‐13Rα1, and IL‐13Rα2 and the phosphorylated levels of c‐Jun, c‐Fos, AKT, and ERK were elevated compared with those in normal lung tissues." (PMID 34758182, 2022).
renal cell carcinoma (3 papers, 2019 to 2021). "In renal cell carcinoma cells, knock-down of IL4Rα or IL13Rα1 and pharmacological inhibition of JAK2 induced cell cycle arrest and apoptosis of cancer cells." (PMID 33419470, 2021). "In renal cell carcinoma cells, knock-down of IL4Rα or IL13Rα1 induced cell cycle arrest and apoptosis by suppressing JAK2-mediated phosphorylation of FOXO3." (PMID 33419470, 2021). "Previously, we reported a close relationship between type II IL4Rα and IL13Rα1 complex and poor outcomes in renal cell carcinoma (RCC)." (PMID 33917914, 2021).